PAX9 (paired box 9)
Diseases named in the same sentence as PAX9 in open-access papers (continued):
Sharing a sentence is not in itself a finding about the gene and the disease.
Oligodontia (32 papers, 2008 to 2025). The absence of six or more teeth from the normal series by a failure to develop. "Case 1 represents classical isolated oligodontia with bilateral symmetrical tooth absence, consistent with autosomal dominant inheritance patterns associated with PAX9 mutations." (PMID 40995403, 2025). "We believe this study will not only expand the mutational spectrum of PAX9 mutations in oligodontia but also strengthen the diagnostic power related to the identified silent mutation." (PMID 38392624, 2024). "Among the genes causing non-syndromic oligodontia, mutations in the PAX9 gene have unique phenotypic characteristics." (PMID 38392624, 2024). "In conclusion, we identified novel PAX9 mutations causing non-syndromic oligodontia through candidate gene sequencing or whole exome sequencing." (PMID 38392624, 2024). "Heterozygous mutations in the MSX1 or PAX9 gene cause oligodontia; therefore, they share an autosomal dominant inheritance in humans." (PMID 38392624, 2024). "This study will not only expand the mutational spectrum of the PAX9 mutations in oligodontia but also improve diagnostic confidence related to the identified silent mutation." (PMID 38392624, 2024). "In humans, mutations in WNT10A are the most commonly reported in the genetic etiology for syndromic oligodontia, and PAX9 mutations are the most commonly reported genetic etiology for isolated oligodontia." (PMID 38132417, 2023). "PAX9 was among the earliest genes to be associated with autosomal dominant forms of oligodontia in humans." (PMID 37056289, 2023). "Missense variants lead to oligodontia of permanent teeth with unaffected primary dentition, supporting the view that the PAX9 variant phenotype is dosage-dependent." (PMID 37056289, 2023). "Patients with heterozygous frameshifts, nonsense and missense mutations in PAX9 commonly present with non-syndromic hypodontia or oligodontia, but although reports of PAX9 deletions are infrequent, some do include heart defects." (PMID 34615475, 2021). "WNT10A mutations are the most commonly reported in the genetic etiology for syndromic oligodontia and PAX9 mutations are the most commonly reported genetic etiology for isolated oligodontia." (PMID 34593752, 2021). "Mutations in PAX9 typically show a nonsyndromic autosomal dominant mode of inheritance for oligodontia, with variable expressivity within families." (PMID 33693441, 2020). "In these genes, NKX2-1 deletion is responsible for choreoathetosis, hypothyroidism, and neonatal respiratory distress and haploinsufficiency of PAX9 causes oligodontia phenotype." (PMID 32595695, 2020). "Variation of Pax9 mutant alleles causes oligodontia, hypoplastic or missing lower incisors and third molars in mouse." (PMID 25897685, 2015). "Numerous different mutations in two transcription factors, MSX1 and PAX9, have been identified in families affected by oligodontia." (PMID 24316698, 2014). "In this study, we identified two novel PAX9 mutations causing non-syndromic oligodontia." (PMID 38392624, 2024). "In this study, we identified two novel PAX9 mutations in two non-syndromic oligodontia families." (PMID 38392624, 2024). "We performed functional analyses of the PAX9 variants to explain the oligodontia phenotype." (PMID 37056289, 2023). "Previous studies have shown that PAX9 is associated with autosomal dominant forms of oligodontia but the precise molecular mechanisms are still unknown." (PMID 37056289, 2023). "Indeed, PAX9 mutations are the most prevalent mutation in patients with nonsyndromic tooth agenesis (including oligodontia;)." (PMID 32813698, 2020). "The EDARV370A genetic variant was associated with dental morphology among Uyghurs, and PAX9 and MSX1 gene mutations were related to non-syndromic oligodontia in Uyghurs." (PMID 40365427, 2025). "Oligodontia can be caused by mutations in various genes involved in tooth development, like AXIN2, MSX1, and PAX9." (PMID 40136761, 2025).
Oligodontia (continued). "Of all these, MSX1, PAX9, EDA, and AXIN2 genes are most frequently associated with nonsyndromic hypodontia or oligodontia." (PMID 40995403, 2025). "In this study, genes associated with oligodontia (MSX1, PAX9, AXIN2, and WNT10A) were analyzed in both the patient and her relatives with oligodontia, revealing the same mutation in the initial codon of the PAX9 gene." (PMID 40692763, 2025). "Mice with knockouts of MSX1, PAX9, and EDA, which are the causative genes of oligodontia in humans, demonstrate developmental arrest of tooth formation or a decrease in tooth number." (PMID 36833267, 2023). "In mouse models, dose effects of the Pax9 gene through downregulation of mRNA transcription are shown to influence the severity of oligodontia." (PMID 37056289, 2023). "At least eight genes have been identified as the major causes of non-syndromic oligodontia (NSO): MSX1, PAX9, AXIN2, WNT10A, LRP6, EDA, EDAR, and WNT10B." (PMID 37056289, 2023). "The PAX9 transition leading to premature stop codon formation (p.Gln136Ter) was described previously in a Finnish family with non-syndromic oligodontia." (PMID 36294409, 2022). "Another study showed evidence that low levels of PAX9 expression, has effects on tooth morphogenesis and generates non-syndromic form of oligodontia in mice." (PMID 24316698, 2014). "To date, mutations in two transcription factor genes, PAX9 (14q12–13) and MSX1 (4p16.1), have been shown as the major causes of non-syndromic oligodontia." (PMID 18545687, 2008). "Koskinen et al31 showed changes in PAX9 similar to patients with multiple agenesis or oligodontia." (PMID 32895649, 2020). "Moreover, genetic mutations of PAX9 and MSX1 cause oligodontia, known as the developmental failure of ≥6 teeth." (PMID 30931425, 2019). "Mutations in numerous genes including msh homeobox 1 (MSX1), paired box 9 (PAX9), Wnt family member 10A (WNT10A), axis inhibition protein 2 (AXIN2), ectodysplasin A (EDA), and Wnt family member 10B (WNT10B) have been associated with nonsyndromic oligodontia." (PMID 30134957, 2018). "In addition to PAX9 and MSX1, AXIN2, which encodes a Wnt-signaling regulator, is reported to associate with oligodontia and colorectal neoplasia." (PMID 18545687, 2008). "However, PAX9 mutations often result in oligodontia, which affects tooth development but does not usually affect the rest of the craniofacial skeleton." (PMID 32813698, 2020). "In the present study, we investigated six genes (MSX1, PAX9, AXIN2, WNT10A, EDA and EDARADD) in a patient with sporadic non-syndromic oligodontia." (PMID 26406231, 2015). "We found a missense variant in AXIN2, but detected no pathogenic variants in MSX1, PAX9, EDA, EDAR, or EDARADD, genes that previously have been found in nonsyndromic oligodontia." (PMID 32234057, 2020). "The transcription factor genes MSX1 and PAX9 were the first and second genes to be identified in non-syndromic oligodontia." (PMID 26406231, 2015). "In addition, these authors suggest that a combined reduction of PAX9 and MSX1 gene dosage in humans may increase the possibility of oligodontia." (PMID 24316698, 2014).
Hypodontia (25 papers, 2009 to 2025). The absence of five or less teeth from the normal series by a failure to develop. "Some of the studies reported MSX1 and PAX9 mutations in molar and bicuspid agenesis, and the PAX9 gene was positively associated with hypodontia susceptibility." (PMID 31781599, 2019). "As far as PAX9 rs61754301 and rs4904155 SNPs are considered, our findings were not significant as it seems that these polymorphisms have no influence on the expression of hypodontia in our subjects." (PMID 31781599, 2019).
cleft palate (7 papers, 2019 to 2023). Cleft palate is a fissure type embryopathy that affects the soft and hard palate to varying degrees. "Dysfunction of PAX9 has been previously associated with the development of craniofacial abnormalities, such as cleft palate and tooth agenesis." (PMID 34684112, 2021). "PAX9 gene mutations have been associated with oligodontia, tooth agenesis, and the development of cleft palate." (PMID 34684112, 2021). "Msx1, Meox2, and Pax9 genes display distinct expression patterns during mammalian palatogenesis and mutations in these genes cause developmental defects, typically a cleft palate." (PMID 32850780, 2020). "Pax9 is expressed in a posterior to anterior gradient in the palatal mesenchyme and studies on Pax9−/− mice have revealed cleft palate associated with defects in palatal growth/elevation, while expression of Bmp4, Msx1, Fgf10 and Osr2 was reduced in the palatal mesenchyme." (PMID 35226783, 2022). "We therefore considered that the cleft palate seen in all neonates with a Pax9–/– genotype may be causing the neonatal lethality as mutant mice with cleft palate die within 24 h of birth." (PMID 34615475, 2021). "Mann–Whitney U test indicated a statistically significant difference for the number of PAX9-positive cells within the connective tissue between the control group and the isolated cleft palate affected tissue group (U = 18.5, p = 0.001)." (PMID 34684112, 2021). "The Mann–Whitney U test notified a statistically significant difference for the number of PAX9-positive epitheliocytes in the surface epithelium between the control group and the isolated cleft palate affected tissue group (U = 2.5, p < 0.001)." (PMID 34684112, 2021). "PAX7 is more associated with the formation of unilateral cleft lip, while PAX9 relates more towards the isolated cleft palate." (PMID 34684112, 2021). "The median number of PAX9-positive epitheliocytes in the surface epithelium of isolated cleft palate affected tissue was a barely detectable number of positive cells (0/+) and ranged from no positive cells to moderate (++) number of PAX9-containing cells." (PMID 34684112, 2021). "We selected eight genes associated with cleft palate (i.e., fibroblast growth factor receptor (FGFR), epidermal growth factor (EGF), PAX9, and tumor protein p63 (TP63))." (PMID 31480549, 2019). "Transcription factors PAX7 and PAX9 are variably involved in the postnatal morphopathogenesis of different facial cleft types: PAX7 is stably associated with the formation of unilateral cleft lip, while PAX9 relates more towards the isolated cleft palate." (PMID 34684112, 2021). "Similarly, a strong correlation was also found between PAX9-positive structures within the epithelium and PAX9-positive structures in the connective tissue in the isolated cleft palate affected tissue." (PMID 34684112, 2021). "The median number of PAX9-positive cells within the connective tissue of the isolated cleft palate patient group was a few (+) immunopositive cells (mainly endothelial cells and some macrophages) and had a range from no positive cells to moderate to numerous (++/+++) in some patients." (PMID 34684112, 2021). "The Kruskal–Wallis H test notified a statistically significant difference for the number of PAX9-positive structures in the epithelium between the control group, unilateral cleft lip group, bilateral cleft lip group, and isolated cleft palate group (H = 28.308, df = 3, p < 0.001)." (PMID 34684112, 2021). "PAX9 has been linked with the formation of cleft lip with or without cleft palate in humans." (PMID 34684112, 2021). "Multiple statistically significant moderate correlations (rs = 0.4–0.6) were discovered between the number of PAX7, PAX9, and RYK-positive structures within the epithelium and connective tissue found in the isolated cleft palate affected tissue." (PMID 34684112, 2021).
cleft palate (continued). "Multiple statistically significant moderate correlations were found between PAX7, PAX9, and RYK within the unilateral cleft lip and isolated cleft palate affected tissue." (PMID 34684112, 2021). "We have also shown that Pax9–/– mice heterozygous for Msx1 have a significantly reduced incidence of arterial duct-dependent defects but an increase in alternative arch artery defects that could have been compatible with post-natal life in the absence of a cleft palate." (PMID 34615475, 2021).
lung carcinoma (7 papers, 2011 to 2025). "From a genomic localization, Pax9 gene sits within Chr 14q13.3, a genomic region which frequently undergoes amplification in lung cancer." (PMID 40506992, 2025). "PAX9 is also amplified and highly expressed in lung cancer, and its knockdown reduced lung cancer formation in a xenograft study, supporting a role in oncogenesis." (PMID 31235851, 2019). "Gain at 14q13 has been studied in relation to lung cancer, and co-amplification and overexpression of the transcription factors TTF-1, NKX2-8, and PAX9 (all located at 14q13) have been associated with cisplatin resistance in lung cancer cell lines." (PMID 21858162, 2011). "Therefore, PAX8 and PAX9 play distinct roles in lung cancer biology, diagnostics, and potential therapeutic applications." (PMID 40506992, 2025). "Overall, PAX9 influences both the cellular behavior and epigenetic landscape of lung cancer, highlighting its dual role as a biomarker and a potential therapeutic target in lung cancer subtypes." (PMID 40506992, 2025). "Regarding PAX8 and PAX9, recent scientific studies have linked these transcription factor to lung cancer, despite their expression not being required in the lung under physiological conditions." (PMID 40506992, 2025). "In addition to ESCC, promoter hypermethylation was also found in lung cancer cells, HNSCC, and ovarian cancer and associated with PAX9 expression and patient survival." (PMID 35628401, 2022). "In lung cancer, amplification of Pax9 promotes cell proliferation of lung cancer cells." (PMID 34195082, 2021). "Studies on PAX9 are needed in various cancers, in particular, HNSCC, ESCC, lung cancer, and cervical SCC." (PMID 35628401, 2022). "In summary, extensive studies on PAX9 in its cellular and tissue contexts are warranted in various cancers, in particular, HNSCC, ESCC, lung cancer, and cervical SCC." (PMID 35628401, 2022). "PAX9 downregulation could make normal cells susceptible to neoplasia, whereas, when cancer has developed, PAX9 amplification and overexpression could also promote the cancer phenotype (e.g., HNSCC, ESCC, and lung cancer), similar to the case of NOTCH in carcinogenesis." (PMID 35628401, 2022).
breast carcinoma (5 papers, 2012 to 2026). "PAX9 downregulation further promoted the cancer phenotype in vitro and was associated with a poor prognosis for breast cancer patients." (PMID 35628401, 2022). "The downregulated expression of PAX9 causes cancer malignancies and is associated with the poor prognosis of breast cancer patients." (PMID 34889888, 2021). "When it turns to the site rs2236007, located in the 14q13.3 loci, the lower expression of the related gene PAX9 was associated with poor relapse-free survival for breast cancer patients." (PMID 34889888, 2021). "At several of the ER+ risk loci, including the 10q26.13-rs2981579 (FGFR2) and 14q13.3-rs2236007 (PAX9) risk loci, we observed interaction peaks that were restricted to the two ER+ breast cancer cell lines and the normal breast epithelial cell line." (PMID 29531215, 2018). "Moreover, the lower expression of PAX9 is significantly associated with the lower survival probability for breast cancer patients." (PMID 34889888, 2021). "Intriguingly, comparative analysis with other PAX family members (e.g., PAX3 and PAX9) revealed that PAX7 exhibits unique oncogenic specificity in breast cancer." (PMID 41532150, 2026). "The rs2236007 G allele in the PAX9 promoter region increased EGR1 binding, which suppressed PAX9 expression in breast cancer cells." (PMID 35628401, 2022). "Meanwhile, the rs2236007 site can decrease the expression level of a breast cancer-related gene, PAX9 (HGNC:8623), via altering the binding of the repressive transcription factor, EGR1." (PMID 34889888, 2021). "The downregulated expression of the PAX9 gene will finally result in a poor prognosis of breast cancer patients." (PMID 34889888, 2021). "For the rs2236007 site, the risk allele G downregulates the PAX9 gene via recruiting the suppressive transcription factor EGR1 and results in malignancy and poor prognosis for breast cancer patients." (PMID 34889888, 2021). "This indicates that the PAX9 gene should be an essential marker candidate in breast cancer management." (PMID 34889888, 2021). "We proved that the lower expression of PAX9 could promote the cell proliferation of breast cancer cells." (PMID 34889888, 2021). "As to the rs2236007 site, the mechanism of PAX9 in terms of resulting in malignancy and poor prognosis of breast cancer is of great importance before the understanding can enter clinical transformation in breast cancer." (PMID 34889888, 2021). "It has been reported that PAX9 protein interacts with the nuclear protein PLU-1 and plays a vital role in the development of breast cancer malignancies." (PMID 34889888, 2021). "In brief, the results indicate that the rs2236007 downregulates the gene expression of PAX9 by affecting the binding of suppressive transcription factor EGR1 and contributes to the malignancy of breast cancer with a poor prognosis for breast cancer patients." (PMID 34889888, 2021). "While being known oncogenes, PAX9 and ZNF143 have not been extensively studied in breast cancer and none of these TFs have previously been implicated in the response to lapatinib." (PMID 22709873, 2012).
orofacial cleft (5 papers, 2014 to 2024). A disorder of facial skeleton that is characterized by cleft lip and/or cleft palate that result in feeding, speech and hearing problems caused by failures during development. "Moreover, PAX9 polymorphisms have been associated with increased orofacial cleft risk in the Asian population." (PMID 38227085, 2024). "Pax7 and Pax9 have been linked to orofacial clefts in mice models and different human studies." (PMID 38227085, 2024). "Multiple different cleft candidate gene interactions and mutations have been associated with the development of craniofacial clefts, for example, the involvement of paired box (PAX) genes such as PAX7 and PAX9 in some orofacial cleft cases." (PMID 34684112, 2021). "In mice models, impaired Pax9 function has been reported to result in an orofacial cleft." (PMID 38227085, 2024). "PAX9 is necessary for the formation of the small ribosome subunit and depletion or dysfunction of PAX9 leads to the disruption in cranial neural crest cell development, leading to the formation of craniofacial anomalies, including orofacial clefts." (PMID 34684112, 2021). "Transcription factors paired box 7 and 9 (PAX7, PAX9) and receptor-like tyrosine kinase (RYK) have been previously associated with the formation of orofacial clefts but their exact possible involvement and interactions in the tissue of specific cleft types remains uncertain." (PMID 34684112, 2021). "No orofacial cleft or other craniofacial abnormalities and no PAX9 gene variations were present in any members of the families of these two cases." (PMID 25101640, 2014).
chronic lymphocytic leukemia (3 papers, 2017 to 2022). "In an analysis of chronic lymphocytic leukemia based on the mutational status of the immunoglobulin heavy chain variable gene (unmutated = 39 vs. mutated = 54), significantly higher PAX9 mRNA expression was found in the unmutated subgroup." (PMID 35628401, 2022). "The high expression of PAX9 (HR: 3.29, p = 0.016) was also predictive of shorter overall survival in patients with chronic lymphocytic leukemia." (PMID 35628401, 2022).